CD34 (CD34 molecule)
Diseases named in the same sentence as CD34 in open-access papers (continued):
Sharing a sentence is not in itself a finding about the gene and the disease.
HIV-1 infection (continued). "We discovered that HIV-1 infection depleted CD34+CD38- early HPCs and functionally impaired human CD34+ HPCs in the BM of patients and humanized mice with HIV-1 infection." (PMID 28759657, 2017). "The new model is based on the fact that immunodeficient mice transplanted with human hematopoietic CD34+ stem cells (HSC) (hu-NSG) at birth enable long-term engraftment of a functional human immune system and support chronic HIV-1 infection." (PMID 25523827, 2014). "CD34+ HSC transduction with this HRH chimeric isoform originated normal macrophages in vitro, normal T cells in vivo, and hindered HIV-1 infection of CCR5- and CXCR4-tropic HIV-1 clones." (PMID 24167505, 2013). "HIV-1 infection was also impaired in other humanized immunodeficient mouse line, the NOD-RAG2−/-γc−/−strain, when these mice were engrafted with CD4+ T cells or CD34+ HSCs transduced with huTRIM5Cyp." (PMID 24167505, 2013). "Rag2−/−γc−/− animals lack B, T, and NK cells, can be engrafted with either CD4+ T cells or CD34+ HSC, and in both cases, support HIV-1 infection." (PMID 24086129, 2013). "Nonetheless, the possibility of the CCR5-tropic HIV infection of progenitors cannot be excluded, as previous studies have revealed the expression of CCR5 in G-CSF/GM-CSF-mobilized CD34+ peripheral blood cells and the subsequent CCR5-tropic HIV-1 infection of megakaryocytes derived from these cells." (PMID 39354676, 2025). "By contrast, the CD34+ cell subsets are decreased in PB of HIV-positive individuals suggesting that the mechanisms upon HIV-1 infection on CD34+ and CD133+ cells are different but are concurrent since both cell subsets seem to be resistant to HIV-1 infection." (PMID 33102251, 2020). "Chronic HIV-1 infection preferentially depleted CD34+CD38- early HPCs in the BM and reduced their proliferation potential in vivo in both HIV-1-infected patients and humanized mice, while CD34+CD38+ intermediate HSCs were relatively unaffected." (PMID 28759657, 2017). "After 22 weeks of CD34+ cell transplantation in NSG mice, we investigated the lymphoid structure formation and development of human leukocytes, which is essential for elicitation of immune responses against foreign antigens and the spread of HIV-1 infection." (PMID 22675567, 2012). "HIV-1 infection studies performed on peripheral blood–derived CD34+ cells generated similar results but also failed to address the purity and differentiation state of the initial CD34+ target cell population." (PMID 19112504, 2008). "We showed that HIV-1 inhibits the differentiation of human CD34+ cells, and this virus-induced hematopoietic inhibition occurs independent of and in the absence of productive virus infection of the CD34+ cells, which we have shown to be resistant to HIV-1 infection." (PMID 38721526, 2024). "Interestingly, an increased presence of CD34+ DNAM-1brightCXCR4+ cells was found in chronic viral infections, including HIV-1 infection, which may reflect chronic hyperactivation." (PMID 36230931, 2022). "To confirm CD34+ cell engraftment and productive HIV-1 infection, we analyzed HIV positive and HIV negative mouse livers, spleens, and LN tissues for the presence of human T cells and for expression of viral p24 by Airyscan confocal microscopy before proceeding with functional assays." (PMID 34717655, 2021). "While HIV-1 infection after mucosal challenge has been reported in CD34 mice, this has not been extendable to all strains of CD34 mice and the low mucosal transmission efficiency in CD34 mice has been attributed to the low human cell reconstitution in the GALT of these mice." (PMID 33673566, 2021). "Thus, we hypothesized that pDCs may be responsible for the depletion of CD34+CD38- early HPCs and their functional impairment during chronic HIV-1 infection." (PMID 28759657, 2017).
HIV-1 infection (continued). "In contrast, pDC depletion did not influence the percentages of CD34+CD38- early HPCs (CD38 expression) and their proliferation in vivo indicated by BrdU expression in the BM in the absence of HIV-1 infection." (PMID 28759657, 2017). "Of note, CXCR4 was more widely expressed on multipotent CD34+ cells than CCR5, and its sole expression renders these cells permissive to HIV-1 infection when the sole expression of CCR5 could not." (PMID 33102251, 2020). "Although a previous study suggested that HIV-1 has the potential to infect intermediate CD34+CD38+ HPCs, we found that p24 expression was absent in BM CD34+ HPCs from humanized mice with HIV-1 infection; in contrast, CD3+ T cells showed high levels of p24 expression (10.5%)." (PMID 28759657, 2017). "Summarized data further demonstrated that chronic HIV-1 infection significantly reduced CD34+CD38- early HPCs by nearly 8-fold as compared to the non-infected animals; meanwhile, the proportion of CD34+CD38+ intermediate HPCs was increased from 76% to nearly 100% as shown in the stacked bar graph." (PMID 28759657, 2017).
Hypertension (38 papers, 2009 to 2024). The presence of chronic increased pressure in the systemic arterial system. "In the present study, platelets, which contribute to endothelial repair in conjunction with CD34-positive cells, were inversely associated with height loss among participants with hypertension." (PMID 39621597, 2024). "Platelet count was positively associated with hypertension among participants with a low CD34-positive cell count." (PMID 37511963, 2023). "Independent of known cardiovascular risk factors, handgrip strength was significantly positively associated with hypertension only among participants with high circulating CD34-positive cell count (at or above the median)." (PMID 36528703, 2022). "Hypertension, which induces aggressive vascular repair, acts as a confounding factor on the association between active arterial wall thickening and circulating CD34-positive cell count." (PMID 36528703, 2022). "The positive association between handgrip strength and hypertension is limited to high CD34-positive cells." (PMID 34088260, 2021). "Increased levels of oxidative stress evaluated by γ-GTP are positively associated with hypertension among elderly participants with endothelial repair deficiency, which is associated with lower levels of circulating CD34-positive cells." (PMID 33549053, 2021). "In our previous study, we found that the status of hypertension determines the association between height and CD34-positive cells; a positive association between these factors was observed only in men with hypertension." (PMID 33549053, 2021). "Investigations of the associations between γ-GTP and the two CD34-positive cell groups (high level and low level) on hypertension revealed a significant interaction." (PMID 31785607, 2019). "To investigate the association between HDL and hypertension in relation to the level of circulating CD34-positive cells, we conducted a cross-sectional study of 477 elderly men aged 60–69 years who participated in general health checkup." (PMID 28619079, 2017). "We also revealed a significant association between HDL level and CD34-positive cell level on hypertension, with fully adjusted p values for the effect of this interaction on hypertension at 0.022." (PMID 28619079, 2017). "Although miRs are thought to be involved in arterial remodelling and atherogenesis, the impact of CV risk factors—including hypertension—on miR expression in CD34+CPCs remains to be clarified." (PMID 28301500, 2017). "Since circulating CD34-positive cell count is inversely associated with mortality from cardiovascular disease, the present study suggests that height loss and hypertension status could be efficient ways to evaluate endothelial repair activity." (PMID 39621597, 2024). "In addition, hypertension is induced by angiogenesis inhibitors, and its risk is increased by insufficient numbers of circulating CD34-positive cells." (PMID 37700384, 2023). "Since hypertension has a common etiology with structural atherosclerosis, circulating CD34-positive cell count could influence the association between handgrip strength and hypertension." (PMID 36528703, 2022). "Therefore, physical stress associated with hypertension elevates circulating CD34-positive cells and induces aggressive endothelial repair, which then leads to a reduction in circulating CD34-positive cells." (PMID 34088260, 2021). "Hypertension could act as a strong confounding factor in the association between circulating CD34-positive cells and active arterial wall thickening." (PMID 33549053, 2021). "Previously, we found that lower levels of circulating CD34-positive cells could elevate the risk of hypertension among elderly men." (PMID 33541438, 2021). "Since height could act as a factor for CD34-positive cell production in the elderly, the risk of hypertension for short stature might be caused by disruption of microcirculation associated with a deficiency of angiogenesis." (PMID 33541438, 2021).
Hypertension (continued). "A wasting reduction in circulating CD34+ cells may act as a strong confounding factor in the association between circulating CD34+ cells and active arterial wall thickening for subjects with hypertension." (PMID 32170211, 2020). "In a previous cross-sectional study, the beneficial association of elevated circulating CD34+ cells on endothelial maintenance were revealed to be masked by hypertension, which might be associated with a reduction in CD34+ cell levels." (PMID 32170211, 2020). "To evaluate the production and consumptive reduction of circulating CD34-positive cells in all participants, including those with over-nutrition (BMI≥25kg/m2), we also performed a hypertension status stratified analysis for any associations between platelets and circulating CD34-positiv cells." (PMID 30695751, 2019). "Third, a positive association between γ-GTP and hypertension should be limited to subjects with low CD34-positive cells because those subjects might have a lower capacity for endothelial maintenance." (PMID 31785607, 2019). "Since hypertension and endothelial dysfunction have a bi-directional association (vicious cycle), the status of circulating CD34-positive cells may influence the association between triglycerides and hypertension." (PMID 29165175, 2017). "Since hypertension and endothelial dysfunction have a bidirectional association in which hypertension induces increased arterial stiffness and vice versa, an unfavorable influence on endothelial repair should cause hypertension among subjects with a high level of CD34-positive cells." (PMID 28619079, 2017). "In addition, the function of CD34+ cells in heart failure caused by the combination of lipid overload and hypertension remains unknown." (PMID 39198543, 2024). "Thus, participants with activated vascular repair who have a shortage of circulating CD34-positive cells might be at risk for hypertension because of the lower capacity to reduce peripheral resistance." (PMID 36528703, 2022). "Therefore, we hypothesized that the positive association between handgrip strength and hypertension is observed only in participants with high CD34-positive cells." (PMID 34088260, 2021). "Therefore, hypertension could act as a strong confounding factor in the association between circulating CD34-positive cells and endothelial repair activity, including active arterial wall thickening." (PMID 33549053, 2021). "Even though a significant positive association between γ-GTP and hypertension was observed in participants with low circulating CD34-positive cell counts, no significant positive association between those two variables were observed in participants with high circulating CD34-positive cell counts." (PMID 31785607, 2019). "Our present results are supported by these studies since a vicious cycle exists between hypertension and endothelial dysfunction, and the different associations between circulating CD34-positive cells and platelets and hypertension could be induced by consumptive reduction of the former." (PMID 29724162, 2018). "Since BMI is positively associated with hypertension, and hypertension participates in a vicious cycle with endothelial dysfunction, overweight participants (BMI ≥ 25 kg/m2) should have activated endothelial activity, resulting in elevated circulating CD34-positive cells." (PMID 29165175, 2017). "Our data suggest the possible involvement of resident CD34+ cells in fibroblast generation in the presence of coexisting hypertension and lipid metabolic syndrome." (PMID 39198543, 2024). "With participants in the lowest γ-GTP quartile (Q1) as the referent group, the fully adjusted OR and 95% CI of hypertension for high CD34-positive cell count was 1.46 (0.69, 3.09) for Q2, 1.14 (0.55, 2.34) for Q3, and 1.02 (0.46, 2.28) for Q4." (PMID 36528703, 2022).
Hypertension (continued). "With participants in the lowest tertile of handgrip strength (T1) as the referent group, the fully adjusted OR and 95% CI of hypertension for high CD34-positive cell count was 2.20 (0.84, 5.73) for T2 and 2.92 (1.08, 7.87) for T3." (PMID 36528703, 2022). "This study shows that platelet count acts as an indicator of vascular repair and hypertension reduces circulating CD34-positive cell count due to consumption." (PMID 36528703, 2022). "Among participants with high CD34-positive cells, the fully adjusted ORs of hypertension, systolic hypertension, and diastolic hypertension for the 1 SD increment of handgrip strength were 1.87 (1.20, 2.93), 1.97 (1.23, 3.15), and 1.78 (1.13, 2.82)." (PMID 34088260, 2021). "In our previous study, circulating CD34-positive cells were found to be positively correlated with height limited to participants with hypertension." (PMID 33549053, 2021). "Since antihypertensive medication can reduce physical stress, the use of this medication to treat hypertension should lower the activity of CD34-positive cells in comparison to uncontrolled hypertension or poorly controlled hypertension." (PMID 34088260, 2021). "Among the study population, 128 participants showed low circulating CD34-positive cells (< 0.96 cells/μL) and 131 were diagnosed as having hypertension." (PMID 34088260, 2021). "Patients with hypertension and vascular lesions displayed a reduced number of circulating CD34+ cells." (PMID 34206404, 2021). "Since damage to endothelial cells stimulates the production of CD34-positive cells, CD34-positive cell concentration should be elevated in participants with hypertension." (PMID 30695751, 2019). "And we also reported in previous study that the number of platelets and circulating CD34-positive cells acts as an indicator of the activity of the vicious cycle that exists between hypertension and endothelial dysfunction in elderly Japanese men." (PMID 29487687, 2018). "In addition, high-density HDL cholesterol is positively associated with hypertension in participants with higher level of circulating CD34-positive cells on the assumption that they might have a higher risk of cardiovascular disease which stimulates endothelial repair activity." (PMID 29165175, 2017). "In our previous study, we reported that hypertension masks the beneficial effect of circulating CD34-positive cells as an endothelial repair factor." (PMID 27374094, 2016). "The number of CD34+133+ cells has been found to be reduced in patients with essential hypertension when compared to normotensive individuals." (PMID 21655296, 2011). "We stained heart sections from healthy people and patients with heart failure (with a history of hypertension and hyperlipidemia) using immunofluorescence and found that CD34 costaining for DDR2, POSTN, and FABP4 was greater in the heart failure group than in the control group." (PMID 39198543, 2024). "In our study, CD34-CreER;Rosa26-tdTomato&ApoE-/- mice with angiotensin II-induced hypertension were used to observe the unique functions of CD34+ cells in hyperlipidemia and hypertension-induced cardiac remodeling through single-cell RNA sequencing (scRNA-seq) and genetic lineage tracing." (PMID 39198543, 2024). "In a cross-sectional study, platelet count was significantly positively associated with hypertension among those with low (<median) circulating CD34-positive cell counts but not among those with high circulating CD34-positive cell counts (≥median)." (PMID 37511963, 2023). "A cross-sectional study with 567 men aged 60–69 years indicated that platelet count is an indicator of endothelial repair activity and that the presence of hypertension might mask the beneficial effects of circulating CD34-positive cells." (PMID 37511963, 2023). "Hypertension induces aggressive vascular repair that reduces circulating CD34-positive cell count." (PMID 36528703, 2022).